MSLN (mesothelin)
Diseases named in the same sentence as MSLN in open-access papers (continued):
Sharing a sentence is not in itself a finding about the gene and the disease.
triple-negative breast carcinoma (41 papers, 2014 to 2025). An invasive breast carcinoma which is negative for expression of estrogen receptor (ER), progesterone receptor (PR), and human epidermal growth factor receptor 2 (HER2). "It is of note that high MSLN expression was linked to several key molecular features in the cancer types analyzed, such as triple negative breast cancer and RAS (KRAS or NRAS) mutations." (PMID 33917081, 2021). "Mesothelin expression is associated with tumor aggressiveness in several solid tumors, including mesothelioma, lung adenocarcinoma, triple negative breast cancer and esophageal cancer." (PMID 34332618, 2021). "Identified as a tumor-associated biomarker, mesothelin is more often overexpressed in triple-negative breast cancer (TNBC) than in common luminal breast tumor subtype or normal tissues." (PMID 27514374, 2016). "Mesothelin is a 40 kDa glycoprotein overexpressed in several cancers, including triple-negative breast cancer (TNBC)." (PMID 40293556, 2025). "(2023) taking Mesothelin (MSLN) as their target in triple-negative breast cancer (TNBC), they developed MSLN CAR-NK cells from induced pluripotent stem cells (iPSCs) whose efficiency was tested in several preclinical models." (PMID 38694508, 2024). "This suggests that EVs derived from CAR-T cells targeting MSLN have the potential to be an effective and low-toxicity treatment strategy for triple-negative breast cancer." (PMID 38794316, 2024). "Chimeric antigen receptor (CAR)-carrying EVs encoding mesothelin-targeted and Myc-tagged scFv have successfully inhibited the growth of MSLN-positive triple-negative breast cancer cells." (PMID 37064613, 2023). "Furthermore, CAR-T-Exosomes targeting MSLN exhibit strong affinity for MSLN-positive triple-negative breast cancer and non-small cell lung cancer cells." (PMID 40904456, 2025). "Of these, mesothelin over-expression in triple-negative breast cancer (TNBC) was of primary interest to us, given (i) the CAF rich TME that correlates with poor prognosis, and (ii) the urgent need for development of new therapies due to current lack of targeted and effective treatment options." (PMID 37251405, 2023). "Indeed, we previously validated 99mTc-A1, which is a single-domain antibody-derived imaging agent, as an efficient probe in accurately targeting mesothelin-expressing triple-negative breast cancer." (PMID 31658755, 2019). "PURPOSE: Mesothelin (MSLN), a 40 kDa glycoprotein normally confined to mesothelial cells, is overexpressed in several malignancies, including triple-negative breast cancer (TNBC)." (PMID 41454065, 2025). "Before the emergence of dual-target strategies, several tumor-associated antigens had been explored as single CAR-T targets in triple-negative breast cancer (TNBC), among which Mesothelin (MSLN) has gained substantial attention." (PMID 41348261, 2025). "EVs derived from mesothelin (MSLN)-targeted chimeric antigen receptor T cells (CAR-T) cells have demonstrated efficacy in targeting MSLN-positive and triple-negative breast cancer cells." (PMID 38794316, 2024). "In N = 43 triple negative breast cancer (TNBC) samples, 67% was MSLN positive, while in other sub types comprising 29 ER positive and 27 HER2 positive, this was below 5%." (PMID 26172299, 2015). "The clinicopathologic and prognostic significance of mesothelin expression in triple negative breast carcinomas (TNBC) has not been fully assessed." (PMID 25506917, 2014). "A CD3 and mesothelin targeting molecule (HPN536) has entered phase I clinical trials (NCT03872206); and preclinical models of a CD16 and mesothelin targeting bispecific molecule have demonstrated enhanced NK cell functions against triple negative breast cancer." (PMID 36911670, 2023).
triple-negative breast carcinoma (continued). "Thus, exosomes derived from CAR T cells targeting mesothelin showed surface expression of the respective CARs and CD3 and inhibited the growth of mesothelin-positive triple-negative breast cancer cells which, might be attributed to tumor cell killing by PRF and GRZB." (PMID 35003134, 2021).
colorectal cancer (36 papers, 2015 to 2026). A primary or metastatic malignant neoplasm that affects the colon or rectum. "The expression of MSLN has been associated with unfavorable prognosis and resistance to chemotherapy in patients with colorectal cancer." (PMID 39417449, 2024). "The expression of the protein Mesothelin (MSLN) is highly variable in several malignancies including colorectal cancer (CRC) and high levels are associated with aggressive clinicopathological features and worse patient survival." (PMID 38234761, 2023). "Mesothelin (MSLN) is reportedly associated with the prognosis of colorectal cancer, and growth differentiation factor 15 (GDF15) is reportedly associated with the recurrence and 5-fluorouracil resistance of colorectal cancer." (PMID 34361106, 2021). "Next, we evaluated the cell surface expression of mesothelin by flow cytometry using a panel of gastric and colorectal cancer cell lines." (PMID 39548594, 2024). "Mesothelin expression in gastric and colorectal cancer cell‐lines (n = 5) was analysed using flow cytometry." (PMID 39548594, 2024). "We also confirmed mesothelin expression in a variety of established gastric and colorectal cancer cell lines and demonstrated their sensitivity to killing by hYP218 CAR T cells." (PMID 39548594, 2024). "Recently, it was revealed that ERC/mesothelin is also expressed in colorectal cancer; thus, this protein is expected to be a therapeutic target in colorectal cancer." (PMID 35565327, 2022). "A previous study showed a positive correlation between MSLN expression in primary and metastatic tumours in patients with colorectal cancer." (PMID 36434635, 2022). "Taking the AUC and P.values into account, the ROC curves showed that CHP2 and MSLN genes can play role as high-quality markers in colorectal cancer." (PMID 35333898, 2022). "In this study, we demonstrated that anti-ERC/mesothelin antibody 22A31 suppressed the growth of colorectal cancer cells subcutaneously xenografted on the back of mice." (PMID 35565327, 2022). "This is the first report to show the effectiveness of an anti-ERC/mesothelin antibody for the treatment of colorectal cancer in vivo." (PMID 35565327, 2022). "MSLN is a cell surface protein that is reportedly highly expressed in several types of malignant tumors, including colorectal cancer." (PMID 34361106, 2021). "Highly expressed MSLN induces an increase in cell proliferation in colorectal cancer, as well as worse prognosis." (PMID 34361106, 2021). "A significant association was found between positive MSLN immunostaining and RAS mutations in colorectal carcinomas (p = 0.0010), and triple negative invasive breast carcinomas of no special type (p < 0.0001)." (PMID 33917081, 2021). "In this work, 512 patients with stage III colorectal cancer (CRC) were examined to ascertain the prognostic value of MSLN expression in preoperative endoscopic biopsy specimens." (PMID 33196692, 2020). "Additionally, clinical data analysis indicates that high expression levels of MSLN in stage IV colorectal cancer patients are negatively correlated with the chemotherapy response rate, underscoring the significant role of MSLN in chemoresistance." (PMID 41400642, 2025). "Similarly, recent pathologic studies have shown that mesothelin is highly expressed in a subset of patients with gastric and colorectal carcinomas." (PMID 39548594, 2024). "Therefore, colorectal cancer can also be a potential target of the treatment using an anti-ERC/mesothelin antibody." (PMID 35565327, 2022). "Based on these findings, we assumed ERC/mesothelin-targeting might be beneficial for the treatment of colorectal cancer." (PMID 35565327, 2022). "For example, the high expression of MSLN in colorectal cancer can promote tumor cell proliferation." (PMID 35692779, 2022). "Our results implied that ERC/mesothelin-targeted therapy might be a promising treatment for colorectal cancer." (PMID 35565327, 2022).
colorectal cancer (continued). "For example, MSLN-CAR-T cells could specifically kill various MSLN-positive solid tumor cell lines and release cytokines in vitro and also decreased the growth of MSLN-positive solid tumors (e.g., ovarian, breast, colorectal cancer) in vivo." (PMID 35911706, 2022). "However, considering the mode of action by amatuximab, colorectal cancer and biliary cancer, which were frequently reported to be mesothelin positive in this study, can be potential targets in the future clinical development of amatuximab." (PMID 25502863, 2015). "Thus, MSLN may serve as a specific biomarker for screening patients with TNBC or colorectal cancer prone to liver metastasis." (PMID 41513618, 2026). "In this study, we evaluated the potential of anti‐mesothelin hYP218 CAR T cells for the treatment of gastric and colorectal cancers and understand their phenotypic characteristics in the tumour." (PMID 39548594, 2024). "A phase I clinical trial (NCT03747965) is currently evaluating the safety and efficacy of MSLN-targeting CAR-T cells in patients with advanced solid tumors, including colorectal cancer." (PMID 39417449, 2024). "Currently, ADCs targeting colorectal cancer are mainly monoclonal antibody ADCs, with primary targets including human epidermal growth receptor 2 (HER2), guanylyl cyclase C (GCC), mesothelin, and carcinogenic antigen-related cell adhesion molecule 5 (CEACAM5), and so on." (PMID 40721409, 2025). "Additionally, clinical trials targeting CEA and MSLN in pancreatic (NCT05538195, NCT03323944) and colorectal cancers are ongoing." (PMID 40909948, 2025). "In addition, MSLN and GDF15 were found to be significantly upregulated (fold change = 12.24 for MSLN and fold change = 14.76 for GDF15) in colorectal cancer tissues, as well as to interact with colorectal-cancer-specific enhancers in colorectal cancer cells." (PMID 34361106, 2021). "Studies have demonstrated that MSLN triggers colon cancer progression; thus, MSLN immunohistochemistry is a powerful prognostic tool for colorectal carcinoma and anti-MSLN therapy could be effective in treating MSLN-positive CRC, even at advanced metastatic stage." (PMID 40227616, 2025). "Notably, elevated MSLN expression was similarly detected in colorectal cancer (but not other tumor types) liver metastases, indicating that the dysregulation of MSLN in liver metastases may have cancer type limitations." (PMID 41513618, 2026).
pancreatic ductal adenocarcinoma (34 papers, 2011 to 2025). An infiltrating adenocarcinoma that arises from the epithelial cells of the pancreas. "Mesothelin (MSLN) is a tumor-associated antigen that is overexpressed in pancreatic ductal adenocarcinoma." (PMID 41472732, 2025). "Mesothelin is a membrane-associated protein overexpressed in pancreatic ductal adenocarcinoma (PDAC)." (PMID 31658755, 2019). "Our previous studies demonstrated that mesothelin (MSLN) plays a significant role in pancreatic ductal adenocarcinoma (PDAC) by promoting cell proliferation, migration, and invasion while inhibiting apoptosis." (PMID 40563707, 2025). "A preclinical study combining oncolytic adenovirus Ad-mTNFα-mIL2 (expressing TNF-α and IL-2) with CAR-T cells targeting mesothelin showed significant tumor attenuation in pancreatic ductal adenocarcinoma models." (PMID 40539780, 2025). "(b) Introducing CAR-T cells targeting MSLN in co-treatment with proton radiation therapy: The co-expression of MSLN in pancreatic ductal adenocarcinoma (PDAC) can promote tumor development, metastasis and worse patient outcomes." (PMID 40227616, 2025). "Knowing that mesothelin is expressed in almost all pancreatic ductal adenocarcinomas, its potential role as a therapeutic target to induce TLS formation in PDAC warrants further investigation." (PMID 38361928, 2024). "Like most pancreatic ductal adenocarcinomas, these cells express the tumor target antigen mesothelin." (PMID 36520915, 2022). "MSLN gene was found to be hypomethylated in pancreatic ductal adenocarcinoma, consistent with the inverse correlation between mRNA expression and DNA methylation described in numerous cancers." (PMID 25477701, 2014). "We previously reported that N-ERC/mesothelin is readily detected in the serum of rats bearing pancreas ductal adenocarcinomas." (PMID 25347530, 2014). "Thus, ERC/mesothelin expression can be found in both human and rat pancreas ductal adenocarcinoma." (PMID 25347530, 2014). "Here, we engineered an oncolytic herpes simplex virus type 1 expressing human MSLN (HSV-MSLN) and evaluated its combination with MSLN-CAR T cells in a murine pancreatic ductal adenocarcinoma model." (PMID 40366419, 2025). "A mesothelin-directed CAR-T cell is also evaluated in other mesothelin + tumor cells including lung adenocarcinoma (NCT03054298; NCT02414269) and pancreatic ductal adenocarcinoma (NCT01897415; NCT03323944)." (PMID 33167514, 2020). "An early study from Carl June’s group in Pennsylvania used mRNA electroporated CAR T cells transiently expressing an anti-mesothelin scFv alongside the CD3-zeta chain and the 4-1-BB intracellular domain to treat six patients with metastatic, chemo-refractory pancreatic ductal adenocarcinoma." (PMID 37371056, 2023). "Immunohistochemical staining using two mesothelin (5B2, and MN-1) and three MPF (MPF25, MPF44, and MPF49) antibodies were performed in 218 selected tumor tissues including ovarian serous carcinoma, pancreatic ductal carcinoma, thymic tumors, and malignant mesothelioma." (PMID 28460459, 2017). "To determine whether serum levels of N-ERC/mesothelin correlated with tumor size, we assayed N-ERC/mesothelin levels in homozygous Kras301 rats bearing pancreas ductal adenocarcinomas." (PMID 25347530, 2014). "We next utilized a non-immortalized pancreatic ductal adenocarcinoma patient-derived xenograft (PDX) cell line (PDX1294), which has high expression levels of both Tn antigen and mesothelin." (PMID 41372740, 2025).
malignant mesothelioma (32 papers, 2010 to 2026). A malignant neoplasm of the pleura or peritoneum, arising from mesothelial cells. "Mesothelin, Hyaluronan, Osteopontin and Fibulin-3 are the most promising diagnostic biomarker candidates for malignant mesothelioma." (PMID 32731396, 2020). "In conclusion, we showed that the combination of mesothelin and miR-103a-3p improved the diagnostic performance of a blood-based screening test, resulting in higher sensitivity and specificity to detect malignant mesothelioma." (PMID 25469901, 2014). "The results of this study show that the combination of mesothelin and miR-103a-3p improves the diagnostic performance of individual blood-based biomarker to detect malignant mesothelioma." (PMID 25469901, 2014). "In malignant mesothelioma, OPN has been extensively studied as diagnostic biomarker, frequently in association with another molecule: mesothelin." (PMID 37398648, 2023). "A biopsy obtained 25 d before gavo-cel infusion showed the presence of malignant mesothelioma, epithelioid type, with most tumor cells showing strong positive membranous mesothelin staining." (PMID 37501016, 2023). "Given the overexpression of MSLN in over 80% of total malignant mesothelioma cases, new agents targeting MSLN are under evaluation in clinical trials and are considered a very promising therapy strategy." (PMID 35883451, 2022). "Here we show that Malignant mesothelioma patients have significantly higher level of Galectin-1, Mesothelin, Osteopontin, VEGF, shed SDC-1, MMP-7, HGF, NRG1-β1 and TIMP-1 compared to benign patients." (PMID 32731396, 2020). "Stepwise logistic regression based on biomarker levels showed that MMP-7, Mesothelin and Osteopontin are three variables with a higher predictive value for distinguishing malignant mesothelioma from metastatic adenocarcinoma." (PMID 32731396, 2020). "Based on ROC curve analyses, Galectin-1, Mesothelin, Osteopontin, NRG1-β1 and shed SDC-1 performed the best diagnostic capacity to distinguish malignant mesothelioma from benign effusions." (PMID 32731396, 2020). "GAS5 is verified as an appropriate circulating marker for the supplement of calretinin and mesothelin to detect malignant mesothelioma." (PMID 32435497, 2020). "For the detection of malignant mesothelioma additional markers are needed besides the established panel consisting of calretinin and mesothelin." (PMID 32435497, 2020). "GAS5 was identified in silico and verified in cell lines as well as human liquid biopsies as an appropriate circulating marker for the supplement of calretinin and mesothelin to detect malignant mesothelioma." (PMID 32435497, 2020). "Our results suggest that malignant mesotheliomas express processed mesothelin on the cell membrane because 5B2 and MN-1 typically showed membrane positivity, whereas MPF44 showed predominantly cytoplasmic staining." (PMID 28460459, 2017). "In malignant mesothelioma, overall survival was significantly longer in the cohort of patients with diffuse membranous expression of mesothelin (P < 0.001)." (PMID 28460459, 2017). "In malignant mesothelioma, mesothelin antibodies (5B2 and MN-1) showed membrane positivity, whereas MPF44 showed predominantly cytoplasmic staining." (PMID 28460459, 2017). "Accordingly, MSLN has been identified as a target for immunotherapy for human malignant mesothelioma." (PMID 29059207, 2017). "Amatuximab and HN1 are both anti-MSLN mAbs with potential to be utilised for treatment of human malignant mesothelioma." (PMID 29059207, 2017). "In malignant mesothelioma, 31% (45/143) and 40% (57/143) of cases showed diffuse mesothelin expression with 5B2 and MN-1 immunostaining, respectively." (PMID 28460459, 2017). "Malignant mesotheliomas frequently express mesothelin (MSLN), an immunogenic glycosylphosphatidylinositol (GPI)-anchored cell surface protein." (PMID 29059207, 2017).